CASK (calcium/calmodulin dependent serine protein kinase)
Diseases named in the same sentence as CASK in open-access papers (continued):
Sharing a sentence is not in itself a finding about the gene and the disease.
Rett syndrome (1 paper, 2024). A severe neurodevelopmental disorder affecting the central nervous system. "In the children with SNI, nine had CP (four dyskinetic, three spastic, two mixed), two had Wolf-Hirschhorn syndrome, two had Rett syndrome and one had a Calcium/Calmodulin Dependent Serine Protein Kinase (CASK) mutation." (PMID 38233513, 2024).
sarcoma (1 paper, 2023). A usually aggressive malignant neoplasm of the soft tissue or bone. "Although the expression of CNTNAP4 in this dataset had lowly expressed transcripts, the levels of CNTNAP4 interacting genes (MACF1, MLLT4, FBXO21, CASK) were found to be highly enriched in the Ki67high sarcoma cells, which was found as well to cluster with high MDM2 expression." (PMID 36599925, 2023). "Interestingly, overexpression of these regulatory proteins such as CASK, TIAM1, APBA1, and NRXN, have also been linked with sarcoma progression." (PMID 36599925, 2023).
urinary bladder carcinoma (1 paper, 2019). "As a result, expression levels of CASK (p = 0.024), LAMA2 (p = 0.040), LY6D (p = 0.018), and CLDN4 (p = 0.043) were significantly associated with the overall survival of patients with urinary bladder carcinoma." (PMID 30699951, 2019).
viral infection (1 paper, 2024). "This work provides crucial insights into the intricate interplay between viral infection, cellular signaling, and the host immune response, highlighting CASK’s pivotal role in orchestrating antiviral defenses." (PMID 39850902, 2024). "Future research should investigate CASK’s involvement in regulating immune responses across various viral infections to elucidate its therapeutic potential further." (PMID 39850902, 2024). "These insights not only clarify CASK’s mechanism of action but also underscore its potential as a therapeutic target to mitigate hyperinflammatory responses during severe viral infections." (PMID 39850902, 2024).
Von Willebrand disease (1 paper, 2019). von Willebrand disease (VWD) is a hereditary bleeding disorder caused by a genetic anomaly leading to quantitative, structural or functional abnormalities of the Willebrand factor (von Willebrand factor; VWF). "CASK was not detectable in the control (von Willebrand’s disease), in non-FSGS-related renal-transplant patients, or renal-transplant FSGS patients who did not exhibit recurrence after transplantation." (PMID 31356645, 2019).
neurodevelopmental disorder (20 papers, 2014 to 2026). A behavioral and cognitive disorder with onset during the developmental period that involves impaired or aberrant development of intellectual, motor, or social functions. "Genetic variants in the X‐chromosomal gene coding for the calcium−/calmodulin‐dependent serine protein kinase (CASK) are associated with a neurodevelopmental disorder." (PMID 41321276, 2025). "Variants in the X‐chromosomal gene coding for the calcium−/calmodulin dependent serine protein kinase (CASK) are associated with a neurodevelopmental disorder." (PMID 41321276, 2025). "Thirty-one children and young people with CASK variants were recruited to the UK-based Brain and Behaviour in Neurodevelopmental disorders of Genetic Origin (BINGO) project." (PMID 41039189, 2025). "Recently, a de novo variant of CASK was found to cause a neurodevelopmental disorder in a 9 year-old boy with severe psychomotor delay." (PMID 38978588, 2024). "CASK dysfunction is a promising route towards understanding some of the pathomechanisms behind RTT since it has been linked to neurodevelopmental disorders with overlapping phenotypes with RTT." (PMID 37710353, 2023). "Intracellularly, α- and β-neurexins feature a short cytoplasmic tail that binds to CASK (CAlcium calmodulin-dependent protein Serine Kinase), which is also genetically linked to neurodevelopmental disorders." (PMID 36608123, 2023). "Mutations in the human CASK gene cause a neurodevelopmental disorder; we show that CASK regulates condensate formation of Liprin-alpha 2 and that patient mutations in the CaM kinase domain interfere with Liprin binding and regulation of condensate formation." (PMID 36137748, 2022). "Pathogenic variants in CASK cause X-linked neurodevelopmental disorders with varying phenotypes depending on variant type and inheritance." (PMID 35830857, 2022). "Calcium/calmodulin-dependent serine protein kinase (CASK) is a membrane-associated guanylate kinase (MAGUK) protein that is associated with neurodevelopmental disorders." (PMID 30610199, 2019). "Here we have tested a combination of computational and in vitro approaches to more fully characterize five previously published pathogenic CASK mutations associated with neurodevelopmental disorder - R28L, Y268H, P396S, Y728C and W919R." (PMID 24505460, 2014). "In the current manuscript we analyzed five known missense mutations in CASK associated with neurodevelopmental disorders: R28L, Y268H, P396S, Y728C and W919R." (PMID 24505460, 2014). "Variants in the CASK gene are associated with many neurodevelopmental disorders." (PMID 36092876, 2022). "Together with our previous findings, showing that loss of Neurexin binding or Neurexin-induced oligomerization is a frequent result of pathogenic CASK missense variants; this points strongly to a presynaptic origin of CASK-related neurodevelopmental disorders." (PMID 36137748, 2022). "CASK-related neurodevelopmental disorders span a wide range of phenotypic severity." (PMID 37805506, 2023). "Second, recently synthesized CASK inhibitors may have benefit in treating gastrointestinal cancers but would not help CASK-LOF neurodevelopmental disorders." (PMID 37805506, 2023).
cancer (12 papers, 2009 to 2026). A tumor composed of atypical neoplastic, often pleomorphic cells that invade other tissues. "The results showed that the expression level of CASK was significantly higher in HCC cancer cell lines than in normal cell line." (PMID 34249726, 2021). "We suggested that the overexpression of CASK in GC held significant promise for the advancement of cancer therapy, either in terms of improving diagnosis or predicting prognosis." (PMID 25373785, 2014). "The mechanism by which CASK plays a role in the development of carcinoma is unclear." (PMID 32336950, 2020). "CASK was detected in the nuclei and cytoplasm of carcinoma cells in 38 of 86 CCA tissues in TMA." (PMID 32336950, 2020). "Furthermore, we compared the expression of CASK in 60 paired HCC samples and corresponding normal samples and found that CASK was markedly upregulated in HCC cancer samples." (PMID 34249726, 2021).
tumor (12 papers, 2009 to 2026). "It is worth noting that CASK is associated with tumor activity inhibition as the crucial regulator in the carcinogenesis of CRC." (PMID 33113509, 2020). "CASK may be a tumour suppressor; its low expression is an independent risk factor for a poor prognosis in CCA patients, and so it could be used as a clinically valuable prognostic marker." (PMID 32336950, 2020). "The methylation status of CASK in 296 tumor tissues and 255 adjacent normal tissues were evaluated using Methylation-sensitive high-resolution melting (MS-HRM)." (PMID 33113509, 2020). "Here, we identified CASK as a new direct target of miR-203 and miR-203 exerts its tumor-suppressive function via down-regulating CASK oncogene." (PMID 25373785, 2014). "We also found that CASK expressed significantly higher in H. pylori infected tumor and control tissues." (PMID 25373785, 2014). "Likewise, tumor weight of xenografts derived from CASK suppression demonstrated a superior response to sorafenib compared to controls." (PMID 34249726, 2021). "Then, to determine whether CASK knockout activated autophagic cell death to sensitize HCC cells of sorafenib in vivo, xenograft tumor models of SMMC-7721-sora sg-CASK cells were generated." (PMID 34249726, 2021). "To date, some previous studies demonstrated that CASK closely links to tumor development." (PMID 34249726, 2021). "This also indicates that CASK may be located upstream of tumour-related pathways and may modulate the entire network in a complex manner, showing different roles depending on the type of tumour." (PMID 32336950, 2020). "Furthermore, heterogeneous methylation of CASK occurred more frequently in CRC patients with lower levels of tumor invasion (T1-T3, P = 0.002) and male patients (P < 0.001)." (PMID 33113509, 2020). "Therefore, the potential role of CASK in the process of tumourigenesis or tumour development and its mechanism deserve further investigation." (PMID 32336950, 2020). "For example, BCL9L, P2RX6, RER1, EFNA2, CASK, CERCAM, and PTPRN were demonstrated to promote EMT, metastasis, and invasion of tumor cells." (PMID 35586092, 2022). "In addition, immunohistochemistry analyses of mice tumor tissues also showed that LC3B-II expression, p-JNK expression and p-c-Jun expression were higher in sg-CASK tissues than that in the control tissues with or without sorafenib treated." (PMID 34249726, 2021).
infection (9 papers, 2012 to 2025). The state of being infected such as from the introduction of a foreign agent such as serum, vaccine, antigenic substance or organism. "We observed significantly higher peri-bronchial leukocyte infiltration, alveolar cellularity, and thickening in the lungs of CASK-deficient mice compared to wild-type mice at day 5 post-infection." (PMID 39850902, 2024). "As expected, the number of TUNEL and NeuN double-positive cells was decreased in CASKflox/flox iCre CG cells after the infection with Lenti-CASK (p < 0.0001)." (PMID 40422253, 2025). "Although Lenti-CASK infection reduced p-JNK/JNK compared to the uninfected control, the effect was smaller than that of the JNK-IN-8 administration." (PMID 40422253, 2025). "The increase in BDNF expression in CASK KO CG cells was attenuated by reexpression of CASK by lentiviral infection in CASK KO CG cells." (PMID 37190086, 2023). "We also tested the effect of Lenti-CASK infection on CASK+/+ CG cells." (PMID 40422253, 2025). "This hypothesis is supported by the modular domains of CASK that enable diverse protein-protein interactions, positioning it as a potential regulator of gene expression in response to cellular stress or infection." (PMID 39850902, 2024). "To investigate the impact of CASK on cytokine production, we measured the levels of IFN-β, IFN-α, IFN-6, TNF-α, IL-6, IL-1β and IP-10 in the culture supernatant of macrophages at 12 h post-H5N1-IAV (MOI=1) infection." (PMID 39850902, 2024). "Importantly, siRNA-mediated knockdown of TJP1, CD63, 14-3-3 β, SUMO1 or GLUT4 reduced the infectivity of HCV by more than 50%, whereas knocking down either of the other two proteins (integrin β1 and CASK) did not affect infection of HCV JFH1 5A-Rluc." (PMID 23593195, 2013).
neurological diseases (4 papers, 2013 to 2023). "Since CASK-related neurological disorders occur due to deletion of a single CASK allele in females, we engineered a CASK(+/-) mouse line to model the neurodevelopmental defects." (PMID 27036546, 2016).
CASK also shares sentences with these, for which no sentence is quoted: gastric cancer (3 papers); glioblastoma (3); oesophageal cancer (3); brain diseases (2); brain malformations (2); cholangiocarcinoma (2); Dandy-Walker malformation (2); diabetes (2); Encephalopathy (2); epilepsy syndrome (2); genetic diseases (2); glioma (2); muscle-eye-brain disease (2); Prader-Willi syndrome (2); Primary microcephaly (2); retinopathy (2); Aicardi syndrome (1); Angelman syndrome (1); Baraitser-Winter syndrome (1); bipolar disorder (1); cardiofaciocutaneous syndrome (1); cardiovascular diseases (1); central nervous system diseases (1); cerebellar ataxia (1); cerebellar degeneration (1); cervical cancer (1); Choreoathetosis (1); ciliopathies (1); Co-infection (1); congenital disorder of glycosylation (1).
A further 41 diseases each share a sentence with CASK in 1 paper.